WT1 (WT1 transcription factor)
Diseases named in the same sentence as WT1 in open-access papers (continued):
Sharing a sentence is not in itself a finding about the gene and the disease.
lung carcinoma (52 papers, 2007 to 2026). "WT1 encodes a zinc finger transcription factor that is upregulated in various tumors, including lung cancer." (PMID 41016985, 2025). "In a lung cancer model, a positive feedback loop was demonstrated between the WT1 and the PI3K/AKT signaling pathway, and loss of WT1 led to decreased proliferation and loss of pAKT as well as decreased expression of antiapoptotic BCL2." (PMID 38190392, 2024). "High levels of WT1 IgG antibody expression in lung cancer is associated with a worse prognosis, but when Trop2 is increased in lung adenocarcinomas, it can suppress cancer progression, suggesting downregulation." (PMID 26000093, 2015). "Similarly, human KRAS-dependent lung cancer cell lines respond to WT1 loss by halting proliferation and undergoing senescence." (PMID 35453662, 2022). "The PI3K/AKT-1 pathway has been implicated in WT1 signaling in lung cancer." (PMID 25929687, 2015). "We consider that siRNA against WT1 in combination with DDP treatment might be of potential value for the treatment of human lung cancer, and the associated experiment were undergo." (PMID 24228711, 2013). "Moreover, it was demonstrated that WT1 loss induced senescence and decreased proliferation of lung cancer cells downstream of oncogenic KRAS signalling.STAT3 is constitutively activated in many human tumors such as prostate, lung, brain, breast and pancreatic cancer." (PMID 23936312, 2013). "WT1 was increased in a majority of human primary tumours compared with the corresponding normal tissues, including lung cancer." (PMID 37667197, 2023). "Although some reports have described the function of WT1 in lung cancer over the past few decades, its impacts on the malignant properties (proliferation, migration, invasion and tumour formation) of NSCLC cells have not been fully elucidated." (PMID 37667197, 2023). "WT1 participates in the control of apoptosis, chemoresistance, proliferation and invasion of lung cancer cells via transcriptional modulation of its targets or interaction with the PI3K/AKT signalling pathway." (PMID 37667197, 2023). "Kaplan-Meier plotter-derived survival analysis further showed that higher WT1 expression predicted shorter survival of lung cancer patients." (PMID 37667197, 2023). "For lung cancer, it has been shown that WT1 is overexpressed, and its high IgG antibody expression is associated with unsatisfactory patient outcome." (PMID 37667197, 2023). "DTH was greater in the lung cancer group than in the pancreatic cancer group for all WT1-DC inoculations; there were statistically significant differences for the fourth, fifth, and sixth DTH." (PMID 38143707, 2023). "Their results were obtained in a study of WT1 silencing but with the use of microRNAs on lung cancer cells." (PMID 36960966, 2023). "Clone WT49 showed nuclear WT1 immunoreactivity in four (7.2%) lung carcinomas and in one (10.0%) synovial sarcoma, while clone 6F-H2 showed no nuclear immunoreactivity in any of the tumors, except for malignant pleural mesotheliomas." (PMID 35453662, 2022). "The methylation levels of eight genes (CALCA, HOXA9, RASSF1A, CDKN2A, DLEC1, CDH13, PITX2, and WT1) in ctDNA were significantly higher in lung cancer patients than in non-lung cancer patients." (PMID 31752198, 2019). "Human and mouse lung cancer cells with ablated WT1 reduced proliferation and triggered senescence, highlighting anti-apoptotic consequences of WT1 ectopic overexpression." (PMID 29623275, 2018). "Studies performed on mouse lung cancer cells revealed a WT1-dependent mechanism of oncogenic KRAS induced proliferation." (PMID 29623275, 2018). "In parallel, the expression of WT1 was up regulated under exposure of DDP in lung cancer, which therefore promoted the DDP-induced resistance in cancer patients." (PMID 30131696, 2018). "“KIM_WT1_TARGETS_DN” (P = 0.0064) is related to the oncogene WT1 in lung cancer, and the high expression of WT1 links to an unfavorable impact on the prognosis." (PMID 30577835, 2018).
lung carcinoma (continued). "In different lung cancer cell lines (A549, H1299 and H1650), anti-WT1 shRNA exerted notable tumor reduction 76%, 74% and 69% for lung cancer cell lines." (PMID 29861465, 2018). "Most of studies demonstrate that WT1 is overexpressed in lung cancer cells and WT1 acts as oncogene to promote proliferation and metastasis." (PMID 27821145, 2016). "In the present study, real-time RT-PCR revealed 100% of WT1 positive cases of lung cancer, 56% of them express high levels of WT1, and A549 lung cancer cells also express high levels of WT1." (PMID 24228711, 2013). "In our previous study, we demonstrated the therapeutic potential of intravenously infused WT1-specific CTL clone cells (TAK-1) against human lung cancer cells in vivo." (PMID 23441216, 2013). "In human lung cancers, expression of both WT1 mRNA and WT1 protein has been demonstrated in tumor cells, suggesting the therapeutic potential of WT1 as a target of anti-lung cancer immunotherapy." (PMID 23441216, 2013). "Taken together, the data suggested that in order to demonstrate our proof-of-concept, it would be sensible to employ the CCR2-CCL2 axis in the setting of redirected T cells targeting WT1 and lung cancer." (PMID 23441216, 2013). "Human lung cancer cells variously express a tumor antigen, Wilms' Tumor gene product 1 (WT1), and an inflammatory chemokine, CCL2." (PMID 23441216, 2013). "In the present study, we first demonstrated that isotype C of WT1 was conservely overexpressed in 20 lung cancer patient specimens." (PMID 24228711, 2013). "Next, using a therapeutic xenografted mouse model, we examined in vivo anti-lung cancer reactivity mediated by infused effector cells double-transfected to express both WT1-specific TCR and CCR2." (PMID 23441216, 2013). "In the present study, we demonstrated the WT1-specific anti-lung cancer effect mediated by CD8+ T cells genetically engineered to express WT1-specific TCR originating from TAK-1." (PMID 23441216, 2013). "A549 and PC14 lung cancer cells were transfected with si-WT1 for 24 h and then analyzed for cell cycle distribution by means of flow cytometry." (PMID 24228711, 2013). "We also found that knockdown of WT1 in lung cancer cells induces the cell cycle arrested at the G1 phase, reduces the expression of antiapoptotic genes, whereas this maneuver enhances the expression of proapoptotic genes." (PMID 24228711, 2013). "There was also a study showed that WT1 is over expressed in lung cancer, although in their report, the authors observed a correlation between WT1 expression and patient survival, there was no data showing the implication of WT1 in lung cancer biology." (PMID 24228711, 2013). "In the present study, we examined in detail the anti-lung cancer functionality mediated by double-transfected CD8+ T cells to express WT1-specific TCR and CCR2 against LK79 cells, both in vitro and in vivo." (PMID 23441216, 2013). "We then designed experiment to evaluate the effect of WT1 knockdown on the proliferation of lung cancer cells." (PMID 24228711, 2013). "In this experiment, the pre-transfection of si-WT1 before DDP exposure increased the sensitivity to DDP in lung cancer cells at all concentrations of DDP examined compared with NC pre-treated group." (PMID 24228711, 2013). "The presented mechanism of enhancement of the WT1TCR signaling by NFAT-regulated CAR can be modified to target different WT1-positive tumors, such as ovarian and lung carcinoma, by using inducible CAR specific to surface antigens such as mesothelin, Her2, or folate receptor alpha." (PMID 40735486, 2025). "WT1 is known to be related to the progression of multiple tumors, including lung cancer." (PMID 39199292, 2024). "Interestingly, following treatment with erlotinib in combination with the WT1/MUC1-DC vaccine, the tumor was undetectable by CT analysis for at least 587 days after treatment in a patient with lung cancer with EGFR-mutated adenocarcinoma." (PMID 38336778, 2024).
lung carcinoma (continued). "The WT1 gene is overexpressed in several tumor types, including lung cancer." (PMID 38336778, 2024). "The absence of an increase in DTH and the weaker induction of an effective WT1-specific cellular immune response compared to the lung cancer group indicates that anti-tumor immunity is strongly suppressed in pancreatic cancer, which is consistent with previous knowledge." (PMID 38143707, 2023). "Taken together, EGR1 is potentially involved in transcriptional regulation of TCF21 and the methylation states of EGR1 binding motif may influence the ability of EGR1 or WT1 to bind to TCF21 in lung cancer." (PMID 33859751, 2021). "In lung cancer, WT1 may affect the oncogenesis of lung cancer through the PI3K/AKT signaling pathway." (PMID 34692659, 2021). "WT1 was described as oncogene in lung cancer, among other malignancies." (PMID 34262872, 2021). "DC vaccines targeting Wilms’ tumor 1 (WT1) have been previously shown to be safe and feasible with few adverse reactions in patients with advanced cancer, including colorectal cancer, pancreatic cancer, lung cancer, high-grade glioma, and pediatric cancer." (PMID 31546936, 2019). "At least eight major isoforms of WT1 were isolated from a cDNA library in lung cancer tissues." (PMID 27821145, 2016). "Because miR-193a inhibited metastasis via targeting WT1 protein, which acts as an oncogene in multiple types of cancers including lung cancer, we are interested in examining whether WT1 counteracts miR-193a-induced anti-metastasis." (PMID 27821145, 2016). "Accordingly, knockdown of WT1 reduced the migration and invasion in lung cancer cells." (PMID 27821145, 2016). "Finally, we confirmed the overexpression of WT1 by IHC in 20 lung cancer tissues (11 adenocarcinoma and 9 squamous cell carcinomas)." (PMID 27821145, 2016). "Importantly, a significant inverse correlation between miR-193a and WT1 mRNA expressions was found in lung cancer tissues." (PMID 27821145, 2016). "Therefore, as for the Ex4a(+)WT1 isoform in normal cells, in three of seven paired samples, normal lung tissues expressed the Ex4a(+)WT1 isoform at levels comparable to those in lung cancer tissues." (PMID 26090994, 2015). "Introduction of the CCL2/CCR2 axis successfully potentiated in vivo anti-lung cancer reactivity mediated by CD8+ T cells double gene-modified to express WT1-specific TCR and CCR2 not only via CCL2-tropic tumor trafficking, but also CCL2-enhanced WT1-responsiveness." (PMID 23441216, 2013). "In the present study, in order to examine the potential advantages of co-introduction of a chemokine-chemokine receptor axis for antitumor adoptive immunotherapy, we employed as a model genetically redirected T cells targeting WT1 for the treatment of human lung cancer." (PMID 23441216, 2013). "As well as increased tumor trafficking activity, we demonstrated that the co-introduced CCR2-CCL2 axis might also be advantageous for potentiating target-responsive cytocidal activity, i.e., WT1-specific TCR-mediated anti-lung cancer reactivity." (PMID 23441216, 2013). "WT1 is a well-known tumor antigen expressed to various degrees by human lung cancer cells, and WT1 expression has been shown clinically to have prognostic value in lung cancer patients." (PMID 23441216, 2013). "Collectively, the co-introduced CCR2-CCL2 axis potentiated not only tumor trafficking activity, but also WT1 epitope-responsiveness mediated by these double-transfected CTLs, resulting in enhanced anti-lung cancer functionality in vivo, notably in the phase immediately after therapeutic infusion." (PMID 23441216, 2013). "Therefore, the expression and clinical significance predicted by website tools all indicated that increased WT1 expression might contribute to lung cancer malignancy and poor patient prognosis." (PMID 37667197, 2023). "In addition, higher WT1 levels might serve as a novel prognostic biomarker for lung cancer patients." (PMID 37667197, 2023).
lung carcinoma (continued). "Thus, the anti-drug resistance of YPFS+GF in DDP-treated lung cancer cells might be mediated by the down regulation of WT1/MVP axis, as well as the downstream anti-apoptotic pathway of mTORC2/AKT signaling." (PMID 30131696, 2018). "Because previous data showed that WT1 was increased in hematological malignancies and multiple types of cancers, we then determined whether the expression of WT1 was increased in lung cancer tissues." (PMID 27821145, 2016). "Therefore, inhibiting or degrading WT1 protein might contribute to the clinical treatment for WT1-overexpressed lung cancer patients." (PMID 27821145, 2016). "However, whether the higher expression of WT1 predicted poor metastasis in lung cancer remains controversial." (PMID 27821145, 2016). "Moreover, WT1 siRNA increased DDP induced apoptosis in A549 lung cancer cells." (PMID 24228711, 2013). "In the present study, we found that WT1 is also over expressed in tumor specimens in a high proportion of patients with lung cancer, use directed sequencing we also found that isoform C type of WT1 was conservely expressed in lung cancer barely without mutation." (PMID 24228711, 2013). "So, WT1 may serve as a marker for DDP sensitivity in WT1+ lung cancer cell lines." (PMID 24228711, 2013). "To investigate changes of PMCs, we evaluated the transcriptomes of PMCs (CALB1, WT1, and UPK3B-positive cells) in pleural effusion from patients with congestive heart failure or patients with lung cancer." (PMID 37649596, 2023). "During the WT1-DC treatment period, IPS improves with increasing DTH in the lung cancer group, while IPS worsens in the pancreatic cancer group, which is consistent with the lack of DTH increase." (PMID 38143707, 2023). "Mutual positivity was observed with WT1, and mutual negativity was seen with TTF‐1 or napsin‐A, excluding the possibility of primary lung cancer." (PMID 36808895, 2023). "The results of this study show that DTH was always larger in the lung cancer group than in the pancreatic cancer group, and in the lung cancer group, DTH tended to increase as the number of times WT1-DC was administered increased." (PMID 38143707, 2023). "However, the role of single WT1 isoform in lung cancer is large unknown." (PMID 27821145, 2016). "WT1 directly binds to the AKT promoter and creates a positive feedback loop between WT1 and AKT expression via the P13K/AKT pathway in lung cancer." (PMID 26000093, 2015). "In this study, we found that CC chemokine 2 (CCL2) was produced to variable degrees by human lung cancer cell lines, and that LK79, a HLA-A*2402+ small-cell lung cancer (SCLC) cell line overexpressing WT1 mRNA, produced extremely high amounts of CCL2." (PMID 23441216, 2013). "DDP is a standard chemotherapy reagent for treating lung cancer, our result indicated that DDP is able to inhibit WT1 expression in A549 cells in a dose- and time-dependent manner." (PMID 24228711, 2013). "A HLA-A2402+ human lung cancer cell line, LK79, which expresses high amounts of both CCL2 and WT1 mRNA, was employed as a target." (PMID 23441216, 2013). "In the present study, we have demonstrated both the feasibility and advantages of CD8+ T cells double-transfected to express WT1-specific TCR and CCR2 for the treatment of at least some human lung cancers." (PMID 23441216, 2013). "In the murine models of KRAS-dependent lung cancer, WT1 deletion/suppression led to senescence only in KRAS-expressing cells, and did not impact wild-type cells, while WT1 loss determined reduction in tumor burden." (PMID 35453662, 2022). "In lung cancer cell cultures, TNFα induced similar WT1 cytoplasmic translocation through PKA-dependent phosphorylation and determined the overexpression of protein matrix metalloproteinase-9, which is normally silenced by WT1." (PMID 35453662, 2022).
lung carcinoma (continued). "One investigation, a comparative study between WT1 IHC antibodies, used the newer clone WT49 and the conventional clone 6F-H2 to stain 40 malignant pleural mesotheliomas, 55 lung carcinomas and 10 intrathoracic synovial sarcomas, and their results corroborate with ours." (PMID 35453662, 2022). "We observed mutations in several important pan-cancer drivers not normally associated with lung cancer, including TSC1 in LUAD1 and LUSC5, and WT1 in LUAD6 and LUAD12." (PMID 30348992, 2019). "Consistent with previous report, the level of WT1 in lung cancer tissues was higher than that in paired adjacent non-cancer ones." (PMID 27821145, 2016). "To better understand the role of GSK-3α and examine the critical genes affected by GSK-3α in lung cancer, we initially screened a subset of NF-κB target genes such as MYC, WT1, BIRC2, IL-9, HMOX1, and TERT, which were regulated by a pan-GSK-3 inhibitor AR-014418 in pancreatic cancer." (PMID 27049759, 2016). "In Wilms' tumor, WT1 suppresses the IGF-1R gene, while Trop2 lowers IGF-1R levels in lung cancer." (PMID 26000093, 2015). "Although studies have shown the oncogene WT1 is overexpressed in lung cancer, there is no data showing the implication of WT1 in lung cancer biology." (PMID 24228711, 2013). "Although in this report, the authors observed a correlation between WT1 expression and patient survival, there is no data showing the implication of WT1 in lung cancer biology." (PMID 24228711, 2013). "When CCR2 was transduced together with a TCR specific for WT1 into CD3+ human T cells, double gene-modified CD3+ T cells demonstrated CCL2-tropic tumor trafficking and potentiated antitumor activity against WT1-expressing LK79 lung cancer cells both in vitro and in vivo." (PMID 35432319, 2022). "In addition, a positive feedback loop between WT1 and AKT has been proposed in lung cancer cells." (PMID 30131696, 2018). "Taken together, DDP treatment downregulates the WT1 expression through the PI3K/AKT signaling pathway, and there is a feedback between WT1 and AKT-1; WT1 is involved in cellular proliferation in A549 cells, WT1 inhibition in combination with DDP will provide a new light for lung cancer therapy." (PMID 24228711, 2013). "However, WT1 has not been previously reported in lung cancer cell lines." (PMID 23936312, 2013). "However, whether WT1 can be regulated by miRNAs in lung cancer cells is not fully understood." (PMID 27821145, 2016). "More importantly, no cytoplasmic WT1 immunoreactivity was seen in any of the tumors evaluated by using clone WT49, whereas clone 6F-H2 showed WT1 cytoplasmic staining in 7 (17.5%) malignant pleural mesotheliomas, 17 (30.1%) lung carcinomas, and 5 (50.0%) synovial sarcomas." (PMID 35453662, 2022).